GFAP (glial fibrillary acidic protein)
Diseases named in the same sentence as GFAP in open-access papers (continued):
Sharing a sentence is not in itself a finding about the gene and the disease.
Hyperglycemia (continued). "Indeed, there was a ~ 5-fold and 2.5-fold increase in Iba1+ cells and GFAP+ staining in CIT + CON mice at 18 weeks compared to the 9-week cohort, suggesting ageing supersedes high-fat or hyperglycemia-induced inflammation on the brain." (PMID 30348168, 2018). "GFAP expression in the telencephalon was significantly reduced in the CUMS+D group when compared with that in the control group, further suggesting that the detrimental effects of CUMS exposure on astroglial health in the zebrafish brain predominates over those of hyperglycemia." (PMID 41462586, 2025). "In the immunofluorescence assays, compared with non-diabetic retinas, diabetic retinas displayed hyperglycemia-activated GFAP expression and extension to the outer plexiform layer, which represents activation of Müller glia and is a key pathological event of early DR." (PMID 36782199, 2023). "Therefore, it may be the case that hyperglycemia also induces damage to vestibular hair cells and alterations in IGF-2, GFAP, and Nnat expression in the vestibular nuclei of mice fed HSHFD." (PMID 32012199, 2020). "The increased GAD levels we observed after 8-weeks of hyperglycemia occurred when increases in IKK and GFAP protein levels were no longer significant, possibly due to anti-inflammatory effects of increased GABA levels in brain." (PMID 38983568, 2022).
prion disease (41 papers, 2008 to 2025). A transmissible disease that is caused by a protein that is able to induce abnormal folding of normal cellular proteins, leading to characteristic spongiform brain changes, which are associated with neuronal loss without an inflammatory response. "While the diagnostic potential of CSF GFAP has been previously explored in prion disease, little is known about its diagnostic value in blood." (PMID 38791145, 2024). "Future studies, including asymptomatic individuals at risk of prion disease, should help investigate GFAP dynamics in the presymptomatic disease stage." (PMID 38791145, 2024). "DN COs did recapitulate one hallmark of prion disease, astrogliosis, showing significantly higher levels of S100Beta and GFAP." (PMID 36656833, 2023). "Astrocyte activation was noted as a specific hallmark of prion diseases, with significant upregulation of the glial fibrillary acidic protein (GFAP)." (PMID 36230910, 2022). "Prion disease-associated astrogliosis is also prominent in human prion diseases as shown by the upregulation of GFAP and YKL-40 (or Chitinase-3-like protein 1; CHI3L1)." (PMID 36230910, 2022). "CNS prion disease is accompanied by extensive reactive astrocytosis characterized by high levels of expression of glial fibrillary acidic protein (GFAP), CD44 and the CD44v6 alternative splice variant." (PMID 35852018, 2022). "Historically, studies of the astrocytic response in prion diseases primarily focused on morphological changes associated with reactive astrogliosis and analyses of expression of glial fibrillary acidic protein (GFAP) or its transcripts." (PMID 33546775, 2021). "GFAP is a traditional marker of reactive astrocytes that has been employed for assessing reactive astrogliosis associated with prion diseases." (PMID 33546775, 2021). "Since astrocyte activation was noted as a specific hallmark of prion diseases with significant up-regulation of glial fibrillary acidic protein (GFAP), the impact of its knockout on disease pathophysiology was tested several years ago." (PMID 31118110, 2019). "The GW-23B7 strongly colocalized with the typical histopathological gliosis of prion disease where the prion particles with high β-sheet content are associated with GFAP immunoreactivity in astrocytes." (PMID 29378642, 2018). "Pathway analysis suggested that the gene expression profile was consistent with immune activation and maturation as well as inflammation, an interpretation supported by the observable GFAP positive astrocytes and gliosis associated with prion disease." (PMID 26341492, 2015). "We investigated brain and cervical cord sections from terminally ill tg(PrPΔOR)/Prnp0/0 and wild-type mice for astrogliosis, a pathological hallmark of prion diseases, by immunohistochemical analysis using anti-GFAP antibodies." (PMID 22927985, 2012). "In addition, alongside PrPSc, a hallmark of prion diseases, astrocytosis marker glial fibrillary acidic protein (GFAP), was also significantly upregulated in ME7 scrapie-infected mice." (PMID 40302732, 2025). "When considering the whole sCJD cohort, pl-GFAP was significantly associated with survival (hazard ratio (HR) 1.27 (1.00–1.63), p = 0.050); however, this result lost significance after accounting for known prognostic factors in prion disease." (PMID 38791145, 2024). "Taken together, these data implicated the Ca2+-dependent activation of calpain endoproteases in the ouabain-induced GFAP proteolysis and may indicate that a similar course of events underlies the GFAP cleavage observed in prion diseases." (PMID 34847154, 2021). "The accumulation of PrPsc and elevation of GFAP in the terminal course of TSEs highlight that the association between PrPc and GFAP may contribute to the pathogenesis of prion diseases." (PMID 32992764, 2020).
prion disease (continued). "GFAP up-regulation is a dominant feature of the proteome of prion-diseased brain tissue, and the other three proteins all independently associate with astrocytes and show differential increases in expression as the prion disease progresses to end stage." (PMID 24366862, 2014). "In summary, these data reveal that although CNS prion disease duration is shorter in microglia‐deficient Csf1rΔFIRE mice, this is not accompanied by increased neuronal vacuolation, prion accumulation, or upregulation of GFAP or CD44 at the terminal stage, when compared to infected Csf1rWT mice." (PMID 35852018, 2022). "Finally, the endoproteolytic cleavage of the glial fibrillary acidic protein, a hallmark of late-stage prion disease, can also be induced by CGs, raising the prospect that a loss of NKA activity may contribute to the pathobiology of prion diseases." (PMID 34847154, 2021). "Here, expression of the misfolded scrapie prion and glial fibrillary acidic protein (GFAP) are prion disease markers." (PMID 39958854, 2025). "* Final stage: notably, at the final stage (145 dpi), both GFAP and PrPSc reached relatively high levels, suggesting their involvement in the pathogenesis of prion disease." (PMID 38698886, 2024). "The brains of kiBVIWT mice inoculated with kiBVIE200K or kiBVID178N extract also contained neuropathological indicators of prion disease such as vacuolation and astrocytic gliosis as well as increased GFAP levels." (PMID 39087478, 2024). "Global upregulation of the intermediate filament glial fibrillary acidic protein (GFAP) is observed within the CNS astrocyte population during prion disease." (PMID 38877012, 2024). "In late-stage prion diseases, astrocytes and microglia enter a reactive state often characterized by increased expression of GFAP and Iba1/CD11b, respectively." (PMID 37508542, 2023). "The present results confirm the widely recognized involvement of astrocytes at early clinical stages of prion diseases, as revealed by the altered mRNA expression of many astrocyte markers at 160 dpi, and increased GFAP immunoreactivity at 180 dpi." (PMID 34225562, 2021). "(d) Boxplots displaying translational changes of neurotoxic (A1 signature) and neuroprotective (A2 signature) genes in GFAP+ cells during prion disease (PrD) progression." (PMID 32960170, 2020). "GFAP is necessary for cytoarchitectural changes and distribution of reactive astrocytes in prion diseases, and there is also a GFAP-dependent function of glial filaments in reactive astrocytes." (PMID 32992764, 2020). "Our results demonstrate a significant and largely overlapping increase in the levels of CHIT1, YKL-40, and GFAP in prion disease, AD, and FTLD, thus supporting the idea of a shared CSF neuroinflammatory profile in neurodegenerative dementias." (PMID 31892365, 2019). "In this study, we measured the CSF levels of the glial markers CHIT1, YKL-40 and GFAP and several other biomarkers of neurodegeneration, in AD, prion disease subtypes, and clinicopathological subgroups of FTD/FTLD." (PMID 31892365, 2019). "Reactive astrocytes are a prominent feature in the prion disease affected CNS as revealed by distinct morphological changes and upregulation of glial fibrillary acidic protein (GFAP)." (PMID 31551718, 2019). "Each ND group showed increased levels of CHIT1, YKL-40, and GFAP compared to controls with a difference between prion disease and AD or FTLD limited to YKL-40, which showed higher values in the former group." (PMID 31892365, 2019). "Dealing with prion disease in which astrogliosis is a prominent feature, we assessed also the mRNA levels of GFAP in all our samples." (PMID 29142239, 2017). "Previous studies in murine model of prion disease identified as disease progresses an increase in immunoreactivity of GFAP (glial fibrillary acidic protein), a selective marker for astrocytes." (PMID 28243355, 2017).
prion disease (continued). "CNS prion disease is also accompanied by the induction of reactive astrocytes expressing high levels of glial fibrillary acidic protein (GFAP)." (PMID 28708055, 2017). "As for SERPINA3, GFAP was up-regulated in all prion diseases, with the highest value observed in gCJD patients (FC = 5.2) and iCJD (FC = 5), sCJD (FC = 3), GSS (FC = 2.9, not significant) vCJD (FC = 2.8) and FFI (FC = 2.2)." (PMID 29142239, 2017). "PrP made by glia can theoretically contribute to a natural prion disease process as demonstrated by the finding that transgenic mice expressing PrP directed by a glial fibrillary acidic protein (GFAP) promoter are vulnerable to prion infection." (PMID 24752288, 2014). "Me7-inoculated mice receiving either PBS or ΨGFP injections showed high levels of GFAP labelling in thalamus, testifying to the presence of astrocytic gliosis consecutive to the prion disease alone." (PMID 18648643, 2008). "Higher GFAP levels have been reported to correlate with prion disease in brain tissue." (PMID 39105172, 2024). "Additionally, both mRNA and protein levels of GFAP, along with protein expression of PrPSc, increased progressively over time during the pathogenesis of prion disease." (PMID 38698886, 2024). "Similarly, levels of chitinase-3-like protein 1 (YKL-40) and glial fibrillary acidic protein (GFAP) were higher in prion disease subtypes, FTD, and AD compared to the controls." (PMID 36831264, 2023). "In animals treated with a single dose of PrP-lowering antisense oligonucleotide, astrogliosis remained low even as the drug washed out and animals eventually developed terminal prion disease, and GFAP staining was reduced in treated animals that reached the endpoint." (PMID 36651748, 2023). "There are other markers of neuronal death that can complement the diagnosis of prion diseases, such as α-synuclein, S100b protein, glial fibrillary acidic protein (GFAP), neuron-specific enolase (NSE), and neurogranin, but their diagnostic efficacy is not fully established." (PMID 38133284, 2023). "In addition, molecular markers of neuroinflammation and particularly indicators of astrocyte and microglia activation [such as vimentin, galectin-1, and glial fibrillary acidic protein (GFAP)] were up-regulated in murine prion disease." (PMID 36378750, 2022). "Our IHC analysis showed that the abundance of GFAP+ immunostaining across nine distinct grey matter regions was similar in the brains of conventionally housed or germ-free mice at the terminal stage of prion disease." (PMID 28708055, 2017). "Similarly, GFAP, tubulin, peroxiredoxin 1, cofilin-1, and alpha/gamma enolase are selectively citrullinated in prion disease." (PMID 26441823, 2015). "Thus, the present report limited to GFAP-immunolabeled astrocytes may show only part of the potential morphological and numerical changes in mouse prion disease model, under influence of age and environmental changes." (PMID 28243355, 2017). "The appearance of these genes correlate well with the infiltration of activated GFAP expressing astrocytes plus increased numbers and activation of microglia, and contains the majority of genes previously reported to be differentially expressed in prion disease." (PMID 23144617, 2012). "We reported a marked increase in the pl-GFAP levels of sCJD patients compared to the np-RPD patients and HCs, likely reflecting the significant astrocyte activation occurring in prion disease as a response to PrPSc misfolding and aggregation." (PMID 38791145, 2024). "Analysis of the correlation of these neuropathological markers of CNS prions disease (AIF1 + microglia; CD44+ and GFAP+ astrocytes; PrPd) showed the variance across all the prion agent strain/recipient mouse combinations studied." (PMID 31551718, 2019). "As for GFAP, we found a similar dysregulation pattern as for SERPINA3 among all groups, up-regulation in all prion diseases together with a negligible increase in AD samples." (PMID 29142239, 2017).
prion disease (continued). "In addition, a recent analysis of the hippocampal proteome in ME7 prion disease in correlation with behavioral and cellular dysfunctions at different time points has revealed a predominant astrocytic signature with four upregulated proteins, including GFAP, selectively expressed in astrocytes." (PMID 28243355, 2017). "The characteristic neuropathological signs of prion disease including spongiform pathology (vacuolation), PrPd accumulations, microglial activation (AIF-1 + cells) and reactive astrocytosis (GFAP + cells) were detected in the brains of all the clinically-affected mice from each group." (PMID 31836813, 2019). "Our finding of increased CSF CHIT1 and GFAP levels in prion disease, AD, and FTD compared to controls, but without significant differences between the three NDs, adds consistency to previous studies in smaller cohorts." (PMID 31892365, 2019). "Astrocytosis was identified using glial fibrillary acidic protein (GFAP) antibody in positive animals; an increased number of astrocytes is an early molecular marker and a typical reaction that occurs in prion diseases in response to the presence of damaged neurons." (PMID 29795663, 2018). "In terms of diagnostic value, we confirmed that only YKL-40 demonstrates a moderate accuracy with ≥ 80% sensitivity and specificity in discriminating between controls and AD or prion disease, while neither YKL-40 nor CHIT1 or GFAP has a significant diagnostic value in any other comparison." (PMID 31892365, 2019). "A close relationship between PrPSc and enhanced glial fibrillary acidic protein (GFAP) immunoreactivity at different stages of the disease has been identified, giving morphological evidence of specific astrocytic involvement in the progression of prion disease." (PMID 28243355, 2017). "Interestingly, GFAP-knockout did not influence prion disease outcome." (PMID 36230910, 2022). "Immunostaining of prion disease-affected brains with an antibody against the common (pan) extracellular N-terminus of CD44 surrounded, but did not co-localize, with cytoplasmic and cytoskeletal GFAP." (PMID 31551718, 2019).
hemorrhagic stroke (40 papers, 2012 to 2026). A stroke caused by a bleed on the brain. "We also demonstrated that a higher GFAP level was principally associated with baseline and subsequent hemorrhagic stroke in CADASIL patients." (PMID 32321529, 2020). "Blood biomarkers like glial fibrillary acidic protein (GFAP) have been reported as a reliable diagnostic test for hemorrhagic stroke." (PMID 27043525, 2016). "The incorporation of GFAP into algorithms with D-dimer and clinical scales contributed to maintaining high specificity, particularly by effectively excluding patients with hemorrhagic stroke, in whom GFAP levels are markedly elevated." (PMID 41311168, 2026). "The differential levels of GFAP between ischemic and hemorrhagic stroke can be attributed to the different kinetics of astrocytic cell death." (PMID 40508137, 2025). "The sensitivity of GFAP in identifying patients with hemorrhagic stroke was found to be 25.0% (95% CI 11.5–43.4), while its specificity reached 100.0% (95% CI 98.6–100.0)." (PMID 40649119, 2025). "Glial fibrillary acidic protein (GFAP), an astrocyte-specific protein, shows promise in distinguishing between ischemic and hemorrhagic strokes." (PMID 40356948, 2025). "GFAP can help distinguish between ischemic and hemorrhagic stroke, while NfL levels correlate with neuronal damage and long-term functional outcomes." (PMID 41465199, 2025). "Silver nanostars were incubated with plasma and spiked with glial fibrillary acidic protein (GFAP), a biomarker elevated in hemorrhagic stroke." (PMID 40136933, 2025). "As such, they can help differentiate between ischemic and hemorrhagic strokes (especially GFAP), provide early detection of neuronal or glial damage, and offer insights into patient prognosis." (PMID 39968454, 2025). "Their conclusion was that plasma glial fibrillary acidic protein (GFAP) and NT-proBNP can help in the differential diagnosis between ischemic and hemorrhagic stroke." (PMID 40508137, 2025). "For the optimization steps commercial human plasma was used, alone or mixed with recombinant GFAP protein at different concentrations, mimicking ischemic or hemorrhagic stroke patient plasma." (PMID 40136933, 2025). "As early as 2006, glial fibrillary acidic protein (GFAP) was identified as an important blood‐based biomarker for hemorrhagic stroke." (PMID 41159140, 2025). "The early rate of change in GFAP levels has been reported to be highly correlated to outcome, as well as to discriminate between ischemic and hemorrhagic stroke." (PMID 40900222, 2025). "In hemorrhagic stroke, GFAP levels rise rapidly, peaking within 2–6 h due to early BBB disruption and neuronal damage." (PMID 41227149, 2025). "Conversely, in hemorrhagic stroke, GFAP can be detected in the blood within a few hours due to the rapid breakdown of the blood–brain barrier and early neuronal damage." (PMID 40142325, 2025). "In cases of hemorrhagic stroke, the disruption of the blood-brain barrier leads to a more significant and rapid increase in GFAP levels in the blood." (PMID 37511304, 2023). "At 14 days after hemorrhagic stroke, only Iba-1+ microglia/macrophages exhibited phagocytic inclusions, while few synapses were detected in GFAP+ astrocytes." (PMID 34836962, 2021). "Upregulation of GFAP has been found not only in the course of ischemic but also in the hemorrhagic stroke." (PMID 31701356, 2020). "In our study, GFAP was a good marker for identifying haemorrhagic stroke within 12 hrs after the onset of symptoms, a high blood level being indicative of a haemorrhagic event." (PMID 26081945, 2015). "Other proteins studied previously in hemorrhagic stroke, such as S100B and GFAP, are mainly expressed by astrocytes, macroglial cells that play an important role in the regulation of blood-brain barrier." (PMID 23049835, 2012).